APC (APC regulator of Wnt signaling pathway)
Diseases named in the same sentence as APC in open-access papers (continued):
Sharing a sentence is not in itself a finding about the gene and the disease.
cancer (continued). "In particular, the adenomatous polyposis coli (APC) gene truncating mutations that stabilize β-catenin are highly prevalent in CRC, making APC one of the most mutated genes in human cancers." (PMID 33535557, 2021). "Taken together, these expression patterns are in line with Wnt‐dependent stem cell maintenance in normal tissue, and Wnt‐independent stem cell maintenance and block of terminal differentiation in cancer tissue with APC mutations." (PMID 34409732, 2021). "Dysregulation of Wnt/β-catenin signaling is highly associated with cancer, and mutations in AXIN, APC, and β-catenin often lead to increased cancer formation and metastasis." (PMID 34589484, 2021). "For example, Wnt signaling is frequently upregulated and tightly linked with poor prognosis in cancers, commonly due to inactivating mutations of adenomatous polyposis coli protein (APC) that mediate the ubiquitination and degradation of β-catenin." (PMID 34959397, 2021). "APC mutations have been shown to induce chemoresistance in numerous cancer forms through several mechanisms within the cancer cell." (PMID 34934968, 2021). "The proposed approach to treat APC mutated cancers is the use of G007-LK, LZZ-02, or RK-582 at low dosage in association with the PI3K (BKM120) and the epidermal growth factor receptor (EGFR) (erlotinib) inhibitors for colon cancer treatment." (PMID 34639169, 2021). "Tissue specificity in cancer is best evidenced by hereditary cancer predisposition syndromes in which the underlying gene defects, such as mutations in APC, BRCA1, and VHL, are associated with a high risk of developing tissue-specific cancer types." (PMID 34440884, 2021). "The influence of COL11A1 and its associated gene triggers alteration of APC for around 66.7% that resulted in the overactivation of Wnt signaling pathways leading to cancer development." (PMID 33597969, 2021). "Hypermethylation, however, which is one of the key epigenetic alterations of the APC CpG sequence, is also associated with carcinogenesis in various cancers." (PMID 33968756, 2021). "Overall, our study suggests that aberrant activation of Wnt/β-catenin signalling such as by pathologically important APC mutation directs cancer metabolism and the Warburg effect via PKM2 in CRC." (PMID 33071283, 2021). "Other mutated cancer genes included those involved in Wnt signaling (APC, AMER1), mitogen signaling (KRAS, BRAF), epigenetic modification (ARID1A, ARID2, DNMT3A, NCOA3) and DNA repair (RAD50, BRIP1, ERCC5, RECQL4)." (PMID 33776923, 2021). "To gain the global response of anti-cancer drugs to APC mutation, we classify the effects according to the drug targeting pathway." (PMID 34440086, 2021). "We present a small, but unique, group of non-FAP mesenteric desmoids, some with genetic alterations in cancer associated genes other than APC." (PMID 34359575, 2021). "Published data suggest that upstream Wnt pathway inhibitors such as PORCN inhibitors are less effective in cancer cells with mutations of downstream Wnt pathway components such as APC mutations." (PMID 33923996, 2021). "A small, but unique group of 16 non-FAP mesenteric desmoid was found to harbor genetic alterations in cancer associated genes other than APC, including CHEK2, BLM, ERCC5, MSH6, and PALB2." (PMID 34359575, 2021).
cancer (continued). "The chromosomal instability (CIN) pathway characterised by the Adenomatous Polyposis Coli (APC) gene mutation was one of the earliest described models, and ascribes to both inherited and sporadic cancers." (PMID 34319053, 2021). "As in the Apc+/Min-FCCC model, most sporadic CRCs arise following the loss of APC, resulting in the formation of microadenomas, adenomas, and ultimately carcinomas with elevated Ascl2 expression." (PMID 33671373, 2021). "Cancers with a truncating APC mutation occurred at an average age that was >10 years lower than the wider cohort of BRAF mutant cancers." (PMID 32384699, 2020). "The probability of truncating APC mutation occurring in a BRAF mutant cancer decreases markedly with age from ~60% in patients diagnosed at age 40, to <10% of patients diagnosed at >90 years of age (Logistic Regression p = 3.74 × 10−7)." (PMID 32384699, 2020). "Only 3.9% (14/356) of discordant mutations found in xenografted liver metastases affected cancer-associated genes, including a third hit to APC, which was already biallelically inactivated in Patient #1 samples, and MEGF6 mutation in Patient #2." (PMID 32532289, 2020). "Wnt signaling is frequently deregulated in several cancers by mutations of the cytoplasmic components of the pathway, including APC or β-catenin." (PMID 32486243, 2020). "Collectively, these data indicate that the mutation of both BRAF and APC results in an aggressive and rapidly progressing cancer phenotype and confers a poor prognosis." (PMID 32384699, 2020). "In its initial chemically un-optimized form, C2 selectively reduced viability of β-catenin-driven cancer cells, which harbor APC mutations." (PMID 32415084, 2020). "For example, familial colorectal polyps that will sooner or later progress to cancer are developed due to inherited mutations in some genes, like the APC (adenomatous polyposis coli) gene 559-563." (PMID 32226506, 2020). "We recently assessed a series of 80 BRAF mutant cancers and identified truncating APC mutation in 11% of these cancers." (PMID 32384699, 2020). "Since SG is assumed to eventually diminish while FG is to progress into advanced cancer, we perform master regulator analysis to identify transcription factors that can drive FG to SG such that the majority of APC deficient cells undergo apoptosis." (PMID 33133158, 2020). "It is possible that, upon acquiring an APC mutation, progression to cancer is rapid and, as a result, identifying lesions in a transitional state is rare." (PMID 32384699, 2020).
cancer (continued). "These cancers can be caused by single mutations (germline or mosaic) in, for example, APC or WTX, but also common genetic variation in WNT3, DVL1, and NXN is previously associated with increased cancer risk." (PMID 32328030, 2020). "Genomic instability is a fundamental hallmark of cancer and the role of APC in stabilizing microtubules (MTs) is essential to maintaining chromosomal stability." (PMID 33105836, 2020). "The importance of the Hippo and Wnt pathway in human cancers was first demonstrated when the human tumor suppressor adenomatous polyposis coli (APC) protein was found in association with β-catenin." (PMID 33143142, 2020). "This is likely due to the increased frequency of MSI in BRAF mutant cancers, and the high frequency of the mutations in highly penetrant APC gene in BRAF wild type cancers, reducing the selective pressure on other WNT regulators." (PMID 32384699, 2020). "We next evaluated the relationship between BRAF mutation and APC mutation in further detail, to characterize the clinical and molecular correlates of this subtype of cancers." (PMID 32384699, 2020). "CRC and GC share the same spectrum of the APC gene mutation, exons 14 and 15 are the most frequently mutated region for both cancers." (PMID 32102509, 2020). "Conversely, targeting the upstream molecules of Wnt signaling, e.g., ligands and receptors, was initially considered ineffectual in cancer cells carrying mutations in Wnt signaling downstream (i.e., APC and β-catenin/CTNNB1)." (PMID 33291655, 2020). "Aberrant activation of Wnt signaling is highly implicated in various types of cancer, including colorectal cancer, in human, for example, hotspot mutations of APC, Axin, and β-catenin have been found to drive tumorigenesis." (PMID 32550000, 2020). "APC and the kinetochore associated proteins have been investigated as targets for developing therapeutics for cancer treatment." (PMID 32339198, 2020). "In sporadic cancer, mutations are typically clustered around a mutation cluster region, a narrowly defined hotspot within the APC gene." (PMID 33352971, 2020). "APC mutations were much more common in a minority of BRAF mutant cancers diagnosed at a younger age." (PMID 32384699, 2020). "The most studied WNT pathway mutations in cancers include sporadic mutations in APC and β-catenin genes." (PMID 31765373, 2019). "Expression of miR-135a has also been linked to the activity of the APC gene, which is involved in cancer development." (PMID 31839821, 2019). "Identification of certain variants in genes such as PALB2 or APC have important implications for cancer surveillance in patients and their at‐risk relatives." (PMID 31592449, 2019). "The shared variants included mutations in key genes of intestinal carcinogenesis (e.g., APC K562fs, V782fs, and Q205X), well-known cancer driver mutations (KRAS G12D), and recurrent homopolymer deletions characteristic of MSI tumors (e.g., TGFBR2 K153fs)." (PMID 31779681, 2019).
cancer (continued). "The timely molecular genetic analysis of germline variants and standardized interpretation of the pathogenicity of novel APC variants has a high impact on choice for treatment, cancer prevention, and family genetic counseling." (PMID 31547110, 2019). "WDR76 caused the ubiquitination-dependent proteasomal degradation of both wild-type and oncogenic K-RAS and had suppressive effects on cancer stemness in CRC cell line-derived spheroids harboring both APC and K-RAS mutations." (PMID 31362761, 2019). "The first nuclease-mediated porcine cancer model was created using TALENs to introduce the adenomatous polyposis coli (APC) heterozygous mutation, providing a colon cancer model." (PMID 34691891, 2019). "Care must be taken when analyzing and interpreting hereditary cancer genes known to be mutated in a mosaic pattern, such as APC and PPM1D." (PMID 31269945, 2019). "The activity of ODC is negatively regulated in normal cells, while the loss of function of cancer-related genes, such as Adenomatous polyposis coli protein (APC), enhances polyamine synthesis and activates their acetylation." (PMID 30104641, 2018). "Recent epidemiologic studies have reported an increased risk of cancer among individuals with higher levels of APC, BRCA1, and RASSF1 promoter methylation in tissue or in blood." (PMID 29953441, 2018). "Since we showed that constitutive activation of Snf1 improves spindle morphology and viability of kar9Δ cells, our study suggests investigating the effects of AMPK activation in APC-mutated cancer cells." (PMID 29643469, 2018). "In contrast, in a subgroup of 66 stage II MSS and BRAF wildtype patients, APC methylation was associated with worse cancer-specific survival (HR 2.63 95% CI 1.21–5.68)." (PMID 29564023, 2018). "APC, which is mutated in several cancers, is a well-established negative regulator of CTNNB1 (β-catenin) and WNT signaling." (PMID 30224629, 2018). "The profiling of cancer mutation genes has identified significant differences in APC, ARIDIA, KMT2A, PIK3CA, and PTEN genes between GC patients of Asian and Caucasian." (PMID 29866191, 2018). "Mutation in any of these components (APC, Axin, or β-catenin) leads to inappropriate stabilization of β-catenin, which results in cancer, most notably of the colon." (PMID 30320549, 2018). "Using an NGS cancer panel, we found a previously unreported missense mutation in the 1835 codon of the adenomatous polyposis coli (APC) gene." (PMID 29535845, 2018). "In transgenic C57BL/6J mice, carrying a mutation for the adenomatous polyposis coli (APC) gene, supplementation of diet with olive oil and salmon oil (rich in omega-3 fatty acids) inhibited the cancer development." (PMID 30487390, 2018). "The other cancer-associated markers APC and AKR1B1 showed relatively high methylation levels in epithelial cell lines, whilst no methylation was observed in mesenchymal cell lines." (PMID 30154364, 2018). "The majority of cancer-related APC mutations was detected in a region dubbed mutation cluster region (MCR) resulting in a carboxyterminal truncation." (PMID 29549256, 2018). "The most frequently mutated tumor suppressor gene in human cancers is APC, which is part of the β-catenin destruction complex in the canonical Wnt pathway." (PMID 28708837, 2017). "Our data suggest that USP7 inhibitors can be used for treatment of CID-deleted APC mutated CRCs, as well as for potential preventive therapy for FAP patients carrying germline APC mutations, by delaying cancer onset." (PMID 29045831, 2017).
cancer (continued). "Truncating mutations in APC, causing LoF of the protein, are found in the vast majority of colon cancer tumors and in many other cancers." (PMID 28708837, 2017). "Of significant importance, homozygous variation of the APC gene SNP rs11954856 was associated with higher expression levels of the APC andβ-catenin genes in the cancer tissue." (PMID 29050326, 2017). "Taken together, these potential benefits lend support to our suggestion to examine the use of these inhibitors as anti-cancer agents also in tumors comprising mutated APC." (PMID 28708837, 2017). "The most frequent LoF mutation in human cancers is Adenomatous polyposis coli (APC), causing aberrant activation of the Wnt pathway." (PMID 28708837, 2017). "Included below this threshold of TCF activity are APC1638N/1572T cells, mutated close to the MCR region of the APC gene, which characterizes mutations in many cancer cells." (PMID 28708837, 2017). "Our work suggests that extracellular inhibitors can effectively restore normal Wnt pathway activity in APC-truncated cancer cells, even though these LoF mutations occur downstream of the inhibitory action." (PMID 28708837, 2017). "Aberrant cancer cell proliferation is associated with mutations in oncogenes and tumor suppressor genes like β-catenin and APC and their downstream signaling cascades including the MAPK pathway." (PMID 28099904, 2017). "A number of studies have highlighted conferred dependency on Wnt in a variety of cancers, driven by mutations in APC or β-catenin." (PMID 28588489, 2017). "The most studied WNT pathway mutations in cancers include inherited and sporadic mutations in APC and beta-catenin genes." (PMID 28870231, 2017). "Highly penetrant cancer mutations, such as those observed in the APC or MMR gene mutations in CRC and BRCA1/2 genes in breast cancer, are rare and usually population-specific." (PMID 29212164, 2017). "Our results suggest that extracellular inhibitors can effectively restore normal Wnt activity in APC-mutated cancer cells, even though these mutations occur downstream of the inhibitory action." (PMID 28708837, 2017). "We expect that restoration of normal Wnt pathway activity by the studied inhibitors is also possible in APC-mutated human cancer." (PMID 28708837, 2017). "In carcinomas, β-catenin degradation is often blocked by either loss-of-function mutations of Adenomatous Polyposis Coli (APC) or by β-catenin mutations that render β-catenin stable." (PMID 28223538, 2017). "The high rate of mutation and structural variation in BRAF mutant cancers suggests alteration of these genes is important for progression of serrated pathway cancers, where Wnt activation by APC mutation is uncommon." (PMID 27661107, 2016). "Among them, two cancer risk pathway “APC/C-mediated degradation of cell cycle proteins” and “Defensins” were enriched with nine hallmark-associated GO terms, respectively." (PMID 27991568, 2016). "The current study describes the establishment of FAP hESCs that carry the germline mutation in the APC gene as a novel human in-vitro model that can be used for studying the first steps in cancer development." (PMID 28010732, 2016). "Mutations of APC have now been characterized in approximately 80 percent of sporadic colon tumors, and less frequently in cancer of other tissues such as breast, stomach, and lung." (PMID 27589803, 2016). "The RNF43 wild type cancer cell lines all harbour either APC or β-catenin mutations which would be predicted to render them insensitive to upstream inhibition of the Wnt signal, as was observed." (PMID 27661107, 2016). "Although most of these APC mutations in mice are embryonically lethal, the severity of the cancer predisposition is variable." (PMID 28010732, 2016). "Despite a strong family history of cancer in the index patient, the APC germline mutation was determined to be a de novo event after constitutional sequencing of the patient’s parents." (PMID 27799065, 2016).